IL27 (interleukin 27)
Diseases named in the same sentence as IL27 in open-access papers (continued):
Sharing a sentence is not in itself a finding about the gene and the disease.
prostate adenocarcinoma (2 papers, 2020 to 2022). "We describe our findings on the effects of IL-27 on the gene expression changes of TC2R prostate adenocarcinoma cells." (PMID 32046108, 2020). "Additionally, we examined the efficacy of the IL-27 cytokines modified at the C-terminus in a STAT1-luc reporter assay, where co-transfection of IL-27ns vector augmented the STAT1 activity in both TC2R and Ras/Myc murine prostate adenocarcinoma cells (RM1) cell lines (p < 0.05)." (PMID 32046108, 2020).
Pruritus (2 papers, 2024). Pruritus is an itch or a sensation that makes a person want to scratch. "IL-27 is a member of the IL-6/IL-12 cytokine family, a group that also includes IL-31, a critical mediator in itch generation and cutaneous AD-associated pruritus." (PMID 39301020, 2024). "To further investigate the potential correlation between IL-27 and pruritus, as well as validate the diagnostic value of altered IL-27 expression in BP and PN, we collected clinical samples and systematically analyzed the expression of IL-27." (PMID 39735535, 2024). "Among these, IL-27 emerged as a potential pivotal gene, as its mRNA expression levels strongly correlated with clinical parameters including pruritus scores, immunoglobulin E levels, and eosinophil counts." (PMID 39735535, 2024). "By integrating bioinformatics and machine learning, we pinpointed IL-27 as a critical player in BP and PN pathogenesis, providing new insights into pruritus mechanisms." (PMID 39735535, 2024). "We innovatively identified IL-27 as a novel potential biomarker, correlated with pruritus and inflammation severity." (PMID 39735535, 2024). "Our current findings suggest the importance of IL-27 in peripheral itch signal transmission and may be an important pruritus feature in BP and PN." (PMID 39735535, 2024).
retinal disease (2 papers, 2022). "Studies will also investigate how IL-27 is regulated in the retina, whether it acts directly on photoreceptors and immune cells, and whether it is protective in other retinal disease models." (PMID 36064575, 2022).
small cell lung carcinoma (2 papers, 2017 to 2021). Small cell lung cancer (SCLC) is a highly aggressive malignant neoplasm, accounting for 10-15% of lung cancer cases, characterized byrapid growth, and early metastasis. "TAP1 was involved in IL-27-mediated anti-PD-1 antibody immunotherapy in small cell lung cancer." (PMID 34957213, 2021).
viral hepatitis (2 papers, 2016 to 2020). An acute or chronic inflammation of the liver parenchyma caused by viruses. "All previous data need more studies to evaluate the role of IL-27 in viral hepatitis." (PMID 33381596, 2020).
Vogt-Koyanagi-Harada syndrome (2 papers, 2014 to 2020). "In spite of skin disorders in which IL-27 plasma concentrations have increased, the serum level of this cytokine is reduced in some auto-immune diseases such as Vogt-Koyanagi-Harada syndrome (VKH), Behçet's disease (BD), and SLE." (PMID 32616337, 2020).
abscess (1 paper, 2022). An inflammatory process characterized by the accumulation of pus within a newly formed tissue cavity which is the result of a bacterial, fungal, or parasitic infection or the presence of a foreign body. "In sharp contrast, exogenous expression of IL-27 induces the accumulation of proinflammatory IL-17-producing RORγt+ neutrophils, which leads to decreased abscess formation and increased bacterial clearance at the infection site." (PMID 36028492, 2022). "Collectively, these results demonstrated that IL-27 affects abscess formation and bone osteolysis." (PMID 36028492, 2022). "Interestingly, the effects of IL-27 on abscess formation and bone osteolysis were lost in IL-27 receptor α knockout mice, suggesting a direct role of IL-27/IL-27R signaling in modulating immune and bone cell functions." (PMID 36028492, 2022).
acute graft versus host disease (1 paper, 2022). A syndrome of immunologically mediated tissue damage that may occur following an allogeneic transplant, usually affecting the skin, liver, and GI tract. "However, the precise role of IL-27 in acute graft-versus-host disease is not yet fully understood." (PMID 36109504, 2022).
acute-on-chronic liver failure (1 paper, 2019). Acute-on-chronic liver failure (ACLF) is an extreme condition during the natural history of chronic HBV infection, with a relatively high short-term mortality. "Serum immunoglobulins are frequently increased in patients with chronic liver disease, but little is known about the role of serum immunoglobulins and their correlations with interleukin-27 (IL-27) in patients with HBV-related acute-on-chronic liver failure (HBV-ACLF)." (PMID 31198792, 2019).
African trypanosomiasis (1 paper, 2015). "In the current study, we have identified IL-27 signaling as a novel pathway to maintain this immunological balance in African trypanosomiasis." (PMID 26222157, 2015). "Obviously, IL-27 signaling functions through limiting activation of CD4+ T cells in African trypanosomiasis." (PMID 26222157, 2015). "To evaluate the role of IL-27 signaling during African trypanosomiasis, we first determined whether infection led to increased expression of this cytokine or its receptor." (PMID 26222157, 2015). "Strikingly, infected wild-type mice treated with anti-IL-10R mAb survived significantly shorter than infected IL-27R-/- mice (p<0.01), suggesting that IL-27 and IL-10 may independently regulate inflammatory responses during African trypanosomiasis." (PMID 26222157, 2015). "Thus, both IL-10 signaling and IL-27 signaling are required for survival of mice infected with the parasites via preventing aberrant inflammatory responses, although they function in a distinct manner in African trypanosomiasis." (PMID 26222157, 2015). "Obviously, in the absence of IL-27 signaling, excessive secretions of IFN-γ by CD4+ T cells also mediate liver pathology and mortality, although IL-10 signaling still fully functions and the infected mice produce even more IL-10, in African trypanosomiasis." (PMID 26222157, 2015).
anaphylaxis (1 paper, 2021). An acute hypersensitivity reaction that occurs from exposure to an allergen. "Further studies are needed to identify transcriptional factors for better understanding the mechanism involved in IL-27-medaited anaphylaxis." (PMID 34234781, 2021). "Since IL-27 promoted features of allergic inflammation in an antigen-independent manner, we examined the role of IL-27 in anaphylaxis." (PMID 34234781, 2021).
arbovirus infection (1 paper, 2024). A viral infection that is transmitted by an arthropod. "We propose that this IL27 enhancement of TRIM expression can influence MDM permissibility toward arbovirus infections in human primary macrophages based on our findings." (PMID 38932287, 2024).
Arthralgia (1 paper, 2022). "Importantly, high levels of IL27 correlate with the persistence of CHIKV-dependent arthralgia." (PMID 35223841, 2022).
autism (1 paper, 2023). Persistent deficits in social interaction and communication and interaction as well as a markedly restricted repertoire of activity and interest as well as repetitive patterns of behavior. "The results indicate that the CSF baseline average level of IL27 is significantly lower in the children whose autologous BMAC treatment did not improve the autism score (Group 1)." (PMID 37894761, 2023).
autoimmune type 1 diabetes (1 paper, 2022). Autoimmune disease wherein the body's own immune system attacks and destroys the cells within the pancreas that produce insulin. "Extracellular vesicles are also demonstrated to restrain the expression of inflammatory cytokines including IL-27 in macrophages and delays autoimmune type 1 diabetes in mice)." (PMID 35013123, 2022).
brain edema (1 paper, 2017). Increased intracellular or extracellular fluid in brain tissue. "Most importantly, we found that these effects of IL-27 treatment coincide with its therapeutic benefit in an ICH model, including reduced brain edema and an improvement in acute and sub-acute functional outcomes." (PMID 28928459, 2017). "However, we have also demonstrated here that LTF (a protein whose main systemic source is circulating PMNs) is upregulated in PMNs in response to IL-27 and that LTF, when used therapeutically, protects from ICH-induced brain edema and neural tissue damage." (PMID 28928459, 2017).
candidosis (1 paper, 2011). "To date, there has been limited laboratory research into the role that IL-27 and IL-35 may have in the immune response to candidosis." (PMID 20981280, 2011).
cardiomyopathy (1 paper, 2021). A disease of the heart muscle or myocardium proper. "The gene expression of CXCL9, coding for MIG in monocytes, was also low in patients with cardiomyopathy, suggesting that IL-27/IL-27R and IL-7/IL-7R may be altered in other cell types." (PMID 34061845, 2021). "In response to IL-27, gene expression of TBX21, EOMES, and CXCL9, which are activated downstream of STAT1, STAT3, and STAT5 phosphorylation, was lower in patients with cardiomyopathy (i.e., the G1 and G2 groups) than that in uninfected subjects." (PMID 34061845, 2021). "The low production of polyfunctional T cells in patients with severe cardiomyopathy was not due to enhanced IL-27-induced IL-10 production, but in contrast, IL-10 was only induced in CD4+ T cells of the G0 subject group and in uninfected subjects." (PMID 34061845, 2021). "In vitro treatment of PBMCs with IL-27 and IL-7 improved monofunctional and polyfunctional Th1 responses, accompanied by the induction of IL-10 and Bcl-2 expression in subjects without heart disease but did not improve those in subjects with cardiomyopathy." (PMID 34061845, 2021). "CD4+ T cell responses improved after in vitro treatment with IL-27 and IL-7 only in subjects without signs of heart disease who have a more functional IL-27 and IL-7 axis and less exhausted immune system compared with those in patients with severe cardiomyopathy." (PMID 34061845, 2021).
carotid atherosclerosis (1 paper, 2017). A thickening and loss of elasticity of the walls of carotid arteries that occur with formation of atherosclerotic plaques. "In the present study we show that patients with carotid atherosclerosis are characterized by increased expression of the IL-27 system both in plasma and within the atherosclerotic lesion." (PMID 29176764, 2017). "Herein we show an up-regulation of the IL-27 system in patients with carotid atherosclerosis both systemically (IL-27) and within the atherosclerotic lesion (IL-27 and IL-27R)." (PMID 29176764, 2017). "Our main findings were: (i) Plasma levels of IL-27 were significantly elevated in patients with carotid atherosclerotic disease compared to healthy controls." (PMID 29176764, 2017). "Adding carotid atherosclerosis to the list of potential battlefields for this cytokine augments the need for further studies of IL-27 in human conditions." (PMID 29176764, 2017). "In this study we investigated the expression of IL-27 and its receptor in patients with carotid atherosclerosis and if IL-27 could modulate the inflammatory effects of the NLRP3 inflammasome in vitro." (PMID 29176764, 2017). "We demonstrate increased levels of IL-27 and IL-27R in patients with carotid atherosclerosis." (PMID 29176764, 2017). "Herein we extend these reports by demonstrating increased plasma levels of IL-27 in 140 patients with carotid atherosclerosis, and increased mRNA levels of IL-27 subunits and IL-27RA, as well as increased expression of IL-1β and NLRP3 within the carotid lesion from 159 patients." (PMID 29176764, 2017). "Although in vivo confirmation is needed, our results suggest that IL-27 could interact with the NLRP3 inflammasome also in patients with carotid atherosclerosis potentially contributing to plaque progression." (PMID 29176764, 2017). "Moreover, total loss of IL-27 signaling as in IL-27RA deficient mice, may not necessarily mirror the situation in patients with carotid atherosclerosis with a local increase within the lesion." (PMID 29176764, 2017).
cervical cancer (1 paper, 2018). A primary or metastatic malignant neoplasm involving the cervix. "We originally identified Interleukin-27 (IL-27) as an anti-HIV cytokine in culture media of cervical cancer vaccine-treated cells." (PMID 29343703, 2018).
chlamydial infection (1 paper, 2023). "This study firstly reveals IL-27/IL-27R’s encouraging role in the Th1 response by regulating DCs cytokines during chlamydial infection." (PMID 36985179, 2023). "Collectively, we demonstrate that IL-27 signaling promotes the protective Th1 response by regulating cytokine production from DCs in chlamydial infection." (PMID 36985179, 2023). "IL-27 signaling was recently demonstrated to mediate protective immunity against chlamydial infection." (PMID 36985179, 2023). "As DCs are involved in chlamydial infection and its regulation on T cell responses, we hypothesized that DCs participate in the IL-27/IL-27R’s protective effect during chlamydial respiratory infection." (PMID 36985179, 2023).
Chronic colitis (1 paper, 2016). A chronic inflammatory disease of the large intestine (colon, cecum and rectum). "The IL6ST/gp 130 is known to regulate transduction of proinflammatory cytokines, i.e., IL-6 and IL-27, which their increased production has been reported in CD patients with chronic colitis." (PMID 27065983, 2016).
coronary artery stenosis (1 paper, 2012). "The results indicated that increased IL-27 levels correlated with the severity of coronary artery stenosis." (PMID 22911112, 2012).
cutaneous melanoma (1 paper, 2013). A primary melanoma arising from atypical melanocytes in the skin. "These cases included 15 patients for which the primary cutaneous melanoma was previously analyzed for IL-27 expression." (PMID 24130734, 2013). "Of note, when IL-27 was detected in primary cutaneous melanomas, its expression was maintained in metastatic lesions." (PMID 24130734, 2013). "We analyzed IL-27 expression in 46 cases of invasive cutaneous melanomas." (PMID 24130734, 2013). "In addition, in 4 of the 5 patients for which the primary cutaneous melanoma was negative for IL-27 expression, an upregulation of IL-27 expression was observed in the metastatic lesion." (PMID 24130734, 2013).
eating disorder (1 paper, 2021). A broad group of psychological disorders with abnormal eating behaviors leading to physiological effects from overeating or insufficient food intake. "However, eating disorder psychopathology was negatively associated with concentrations of IL-22, IL-27, MCP-1, MIP-1β and TNF-β, with a moderate effect size, and Eotaxin-3, with a large effect size." (PMID 34442458, 2021).
eczema (1 paper, 2011). "We then studied the regulation of BAFF and APRIL in vitro in keratinocytes using some factors involved in the pathogenesis of eczema and we found that the BAFF mRNA level was dramatically increased by IFN-γ and IL-27." (PMID 21765951, 2011).
emphysema (1 paper, 2016). "Because cigarette smoking is critical to the pathogenesis of COPD, we assessed IL-27 in a smoking mouse model of emphysema." (PMID 27994590, 2016). "We observed that the emphysema in mice receiving anti-IL-27 treatment was ameliorated to a certain extend as compared with which received PBS." (PMID 27994590, 2016). "Thus, our findings contribute to a better understanding of pathogenesis of emphysema induced by cigarette smoke exposure, and targeting IL-27/WSX-1 may provide a new therapeutic approach for COPD." (PMID 27994590, 2016). "In conclusion, here, we have demonstrated that IL-27 was elevated in patients with COPD and in a mouse model of emphysema." (PMID 27994590, 2016). "In the present study, we sought to evaluate the expression of IL-27 and Th1/Th17 cells in patients with COPD and then explore the role of IL-27/WSX-1 on Th1 and Th17 cells differentiation in a smoking mouse model of emphysema." (PMID 27994590, 2016). "In this study, we aimed to evaluate the expression of IL-27 in patients with COPD and explore the role of IL-27/WSX-1 on Th1 and Th17 cells differentiation in a smoking mouse model of emphysema." (PMID 27994590, 2016). "Despite the inhibitory activity of IL-27 on the secretion of IL-17 by naive CD4+ T cells in vitro, IL-27 neutralization did not lead to a more exaggerated IL-17 production in smoking mouse model of emphysema." (PMID 27994590, 2016).
esophageal neoplasms (1 paper, 2021). "Associations with malignancies were found for the IL-27-T4730C polymorphism, which was linked to the susceptibility of developing colorectal, hepatocellular and esophageal neoplasms, but it was found protective for UC." (PMID 35011777, 2021).
fungal infections (1 paper, 2018). "A better understanding of the IL-12 receptor cytokine family, particularly the newer members (IL-27 and IL-35) is invaluable to fully unravel the importance of targeting this family to develop immunotherapies to help fight fungal infections." (PMID 29793796, 2018). "IL-12, IL-23, IL-27 and IL-35 are critical cytokines in innate and adaptive immune responses against fungal infections." (PMID 29793796, 2018). "•IL-27 promotes regulatory effector responses during fungal infections." (PMID 29793796, 2018).
gram-negative bacterial infections (1 paper, 2018). Infections caused by bacteria that show up as pink (negative) when treated by the gram-staining method. "Gram-negative bacterial infection of myeloid cells is well-described to induce IL-27 production; this study describes IL-27 as a key player in enhancing proinflammatory response to infection with S. typhimurium or its components." (PMID 30209294, 2018). "Elevated inflammatory responses upon IL-27 treatment prior to Gram-negative bacterial infection could potentiate greater clearance of infection due to induction of adaptive immune responses." (PMID 30209294, 2018).
Guillain-Barre syndrome (1 paper, 2018). A spectrum of rare post-infectious neuropathies that usually occur in otherwise healthy patients. "IL-23 and IL-27 are believed to be involved in the pathogenesis of Guillain-Barré syndrome (GBS)." (PMID 29434217, 2018).
Headache (1 paper, 2021). Cephalgia, or pain sensed in various parts of the head, not confined to the area of distribution of any nerve. "Regarding the central tendency measures, in the comparison of the crude median values of cytokines, we observed that patients with headache had higher median values of GROa, IFN-gamma, IL-10, IL-13, IL-15, IL-17a, IL-21, IL-22, IL-27 and IL-6." (PMID 34088273, 2021).
hepatitis B infection (1 paper, 2010). "Importantly, it was recently reported that patients suffering from a hepatitis B infection have elevated IL-27 serum levels." (PMID 20719000, 2010).
Hypoglycemia (1 paper, 2025). A decreased concentration of glucose in the blood. "We showed significant levels of hypoglycemia during infection, which is a routine clinical observation and described with our model, and high levels of IL-27 in the sera of mice infected with E. coli in line with our prior report." (PMID 40682363, 2025).
immunotoxicity (1 paper, 2021). "The authors elaborate that the gene expression related to increased PFAS levels was indicative of immunotoxicity because of association with immunomodulatory genes (e.g., CYTL1, IL27)." (PMID 34712855, 2021).
infertile (1 paper, 2020). "Increased levels of inflammatory mediators in the endometrium of infertile patients, including IL-12, IL-15, IL-18, and IL-27, have the potential to influence uNK cell responses and to attract peripheral NK cells." (PMID 32872526, 2020).
influenza A H1N1 virus infection (1 paper, 2020). "For instance, melatonin was found to exhibit therapeutic potential in influenza A H1N1 virus infection, to elicit anti-inflammatory and immune modulatory effects—the induction of IL-10 by melatonin occurs via the upregulation of IL-27 in DC—and to exhibit a synergistic effect with an antiviral drug." (PMID 32911682, 2020).